MCL1 (MCL1 apoptosis regulator, BCL2 family member)
Diseases named in the same sentence as MCL1 in open-access papers (continued):
Sharing a sentence is not in itself a finding about the gene and the disease.
infection (continued). "As expected, transfection of cells with a miR-26a mimic prior to infection, also attenuated the expression of Mcl-1." (PMID 28558034, 2017). "Infection with Ft SchuS4 resulted in significant changes in both antiapoptotic (Bax/Bcl-2, Mcl-1, Bcl-xl, and Bcl-xl/Bak) and proapoptotic markers (Bax, Bak, Bim, and caspase-3)." (PMID 28955505, 2017). "Mcl-1 protein levels strongly increase upon 16 hr post infection (hpi) and remain high until the end of the chlamydial developmental cycle." (PMID 28347402, 2017). "Our results identify a differential role of the anti-apoptotic proteins Bcl-XL and Mcl-1 during infection of mammalian cells with large DNA viruses." (PMID 27537523, 2016). "In HeLa cells, the sole targeting of Mcl-1 by RNAi induced apoptosis, and this was at least partially reversed by infection with MVA." (PMID 27537523, 2016). "Because parental OCI-AML3 cells have relatively high MCL-1 protein expression levels, we generated isogenic OCI-AML3 cells where MCL-1 was downregulated by lentiviral infection using MCL1-specific shRNA." (PMID 26375587, 2015). "We observed an increase in phosphorylation of p38 as well as the ER stress marker GRP-94 following Ad.mda-7 or Ad.CCN1-CTV-m7 infection and a decrease in expression of the anti-apoptotic Mcl-1 protein." (PMID 25926554, 2015). "Extensive apoptosis in avian influenza virus infected PAM was evident by 6 h of infection with caspase activation and reduced Mcl1 expression." (PMID 26642934, 2015). "We have shown that Mcl-1 expression early after infection serves to inhibit the apoptosis of infected cells through the inhibition of caspase-3 cleavage/activation, prior to the 48-hour viability gate." (PMID 24531335, 2014). "The enhanced Mcl-1 production in response to S. aureus was proportional to infection rate and was exerted only by viable bacterial cells." (PMID 23431241, 2013). "A 4-fold increase of MCL1 mRNA was observed 1 h after-infection, with sustained upregulation observed for up to 6 h." (PMID 23431241, 2013). "At the protein level, Mcl-1 levels were significantly increased 2 h after-infection, reached a maximum at 8 h, and remained at 3-fold higher levels compared to mock-infected cells for at least 20 h." (PMID 23431241, 2013). "Lastly, we studied the upstream signaling pathways leading to infection-mediated Mcl-1 induction and identified components of the MAP/ERK, PI3K/Akt and GADD153 in the endoplasmic reticulum (ER) stress pathways as potential modulators." (PMID 22253918, 2012). "In IBV-infected Huh7 cells, a 1.28–2.06-fold and a 1.17–2.06-fold induction of Bak and Mcl-1 from 8–20 hours post-infection was observed." (PMID 22253918, 2012). "A moderate enhancement effect on viral protein synthesis and viral particle release was observed in Mcl-1 knockdown cells infected with IBV in the late stages of infection." (PMID 22253918, 2012). "Quantification of the corresponding bands by densitometry measurement showed a 1.04–4.66-fold and a 0.85–3.92-fold induction of Bak and Mcl-1 In IBV-infected Vero cells from 8–24 hours post-infection, respectively." (PMID 22253918, 2012). "In Vero cells infected with IBV at an M.O.I. of 1, significant up-regulation of both Bak and Mcl-1 was observed at 16 and 24 hours post-infection with an increase in IBV-N protein expression as an indication of infection." (PMID 22253918, 2012). "Northern blot analysis, followed by densitometry measurements, of all three IBV-infected mammalian cell lines showed an induction of both Bak and Mcl-1 transcripts at the mRNA level from 12 hours post-infection." (PMID 22253918, 2012). "Densitometry measurements of the corresponding bands showed a 1.26–2.59 fold induction of Mcl-1 In IBV-infected Vero cells from 8–20 hours post-infection." (PMID 22253918, 2012).
infection (continued). "Mcl-1 and Bak also appear to be involved in regulating viral replication efficiency at late stages of infection, as a decrease in Mcl-1 expression levels and an increase in that of Bak promote virus progeny release." (PMID 22253918, 2012). "Quantification of the corresponding bands by densitometry measurement showed a 1.11–3.66-fold and a 1.10–2.82-fold induction of Bak and Mcl-1 from 8–24 hours post-infection, respectively." (PMID 22253918, 2012). "In chicken fibroblast DF1 cells infected with IBV an M.O.I. of 1, moderate up-regulation of both Bak (1.39–2.09 fold) and Mcl-1 (1.14–1.30 fold) at the transcriptional level were also observed by RT-PCR analysis at 8 and 16 hours post-infection." (PMID 22253918, 2012). "In this study, global gene expression profiles have been first determined in IBV-infected Vero cells at 24 hours post-infection by Affymetrix array, revealing an up-regulation at the transcriptional level of both pro-apoptotic Bak and pro-survival Mcl-1." (PMID 22253918, 2012). "This increase was also quantified by real-time PCR, which, after normalization to mock-infected chicken embryos, showed a 6.41- and 6.43-fold increase in Bak and Mcl-1 induction, respectively, at 48 hours post-infection." (PMID 22253918, 2012). "The elevated expression of MCL1 decreased during the course of infection, yet at 72 h it was still 2-fold higher than that in mock-infected control cells." (PMID 19381294, 2009). "Since BH3-only proteins have been shown to inactivate BH1-4 proteins like Mcl-1, infection-induced upregulation of Mcl-1 and depletion of BH3-only proteins would nicely fit to a general and multi-level inhibition of apoptosis upstream of mitochondria." (PMID 18769617, 2008). "We therefore propose the following model for apoptosis resistance in C. trachomatis-infected cells: During the early phase of infection, Mcl-1 and IAPs are upregulated and stabilized in a MAPK-dependent manner." (PMID 18769617, 2008). "Infection-induced upregulation of Mcl-1 prevents the release of the IAP antagonist Smac/DIABLO whereas IAP upregulation directly prevents the activation of caspases-3." (PMID 18769617, 2008). "M. leprae induced an increase in Mcl-1 expression by 2.9 % at 18 h post-infection with a further (12 %) increase at 48 h." (PMID 16978419, 2006). "Additionally, MCL1 allowed for increased coupling of oxygen to ATP production under infection conditions." (PMID 40464580, 2025). "scRNA-seq of spleen CD8+ TM cells isolated day 7 after LCMVc13 infection showed that anti-apoptotic genes such as Bcl2, Mcl1 and Xiap were diminished, while pro-apoptotic genes like Bax and Bid35,36 were elevated in GFI1ΔCD8 CD8+ T cells compared to WT CD8+ T cells." (PMID 40374731, 2025). "Additionally, we observed that inhibition of Mcl-1 with Umi-77 led to visibly increased pRIP3 levels in infected cells, indicating that Mcl-1 stabilization during infection plays a role in counteracting necroptosis." (PMID 41051248, 2025). "Genes linked to STAT3 during infection were associated with GO terms such as regulation of cell proliferation (CCND1, JUNB), negative regulation of apoptosis (MCL-1, NFKB1), cytokine-mediated signaling pathway (IL10RA, SOCS1), and immune system process (CRK, IRF9)." (PMID 41115066, 2025). "As the infection progresses, other DCs undergo effector-triggered apoptosis due to bacterial blockade of host protein synthesis decreasing levels of the pro-survival proteins Mcl-1 and cFLIP." (PMID 40530878, 2025). "Notably, our findings uncover a previously unrecognized role of neutrophil necroptosis in limiting Chlamydia survival and reveal infection-driven modulation of necroptosis through Mcl-1 stabilization." (PMID 41051248, 2025). "In addition, the HIF-1α stabilization in the early stages of infection contributes to increased Mcl-1 levels." (PMID 41204030, 2025).
infection (continued). "To determine whether Mcl-1 is essential for this effect, we treated neutrophils with Umi-77, a selective Mcl-1 inhibitor, 30 min prior to infection." (PMID 41051248, 2025). "Upregulating MCL-1 in neutrophils, IL-6 allows them to eliminate the pathogen, thereby preventing the efficient viral propagation, the consequent lung damage, and the fatal outcome of the infection." (PMID 38256213, 2024). "Interestingly, MCL-1 regulation is observed and serves as a key event during infections with various types of viruses, which is presented in detail in the following sections." (PMID 38256213, 2024). "Given that MCL-1 regulation of apoptosis requires frequent turn-over of the protein, we hypothesised that the NS3 protein may also be responsible for the loss during infection." (PMID 39226332, 2024). "Following the infection process, after expressing the MCL1 onto the surface of Metarhizium cells to avoid recognition and encapsulation by arthropods immune cells, the fungus can express the MOS1 receptor protein to adapt to the high osmotic pressure of the insect hemolymph." (PMID 39703704, 2024). "It is also possible that had we conducted our analysis at different time points post-infection (hpi), we might have identified additional Cdu1 targets, such as Mcl1 and IκBα which were not identified in our analysis." (PMID 38358795, 2024). "In the context of murine macrophage cell line infection by intramacrophage parasite Leishmania donovani, TCTP was found to be strongly associated with Mcl-1, which prevents ubiquitination-mediated degradation of Mcl-1 and inhibits apoptosis." (PMID 37201583, 2023). "In addition, we observed that MCL-1 stabilized via rKSHV-infection markedly increased cells proliferation, and dramatically reduced apoptosis measured by PI staining." (PMID 33471866, 2021). "Interestingly, these effects were also observed in Mel-HO, although in this cell line Mcl-1 was already strongly downregulated after infection with AdV-TRAIL and induction of TRAIL." (PMID 34028599, 2021). "Notably, BCL-2 and its family genes (BCL-XL, BCL-W, and MCL-1) were upregulated during infection with gamma-irradiated M. tuberculosis infection in BMDMs from WT mice but not in those from NEK6-deficient mice." (PMID 32487755, 2020). "Western blotting results demonstrated that MCL1 was up-regulated after infection with lentivirus." (PMID 33126914, 2020). "Moreover, blockade of epithelial growth factor receptor (EGFR) with specific neutralizing antibodies and pharmacological inhibitors results in the downregulation of Mcl-1 gene expression and shows similar level of cell viability to mock infection." (PMID 32765441, 2020). "Furthermore, we showed that host protein synthesis is impaired in cells upon infection with flaviviruses, leading to the decay of labile proteins such as MCL1." (PMID 30261081, 2018). "Reasons for these differences are unclear, but the extended upregulation of MCL-1 and prolonged activation of PI3K may be linked to the unusual route that HCMV utilises during the infection of monocytes." (PMID 29547547, 2018). "Interestingly, expression of MCL1 decreased upon infection with JEV, DENV and ZIKV, in contrast to the continued stable expression of other BCL2 family proteins." (PMID 30261081, 2018). "M. tb at different MOIs (5 or 10) significantly increased Mcl-1 protein 24 h after infection." (PMID 29928066, 2018). "We showed that expression of pro-survival MCL1 is reduced upon infection with flaviviruses." (PMID 30261081, 2018). "In addition, the suppression of MCL1 expression was enhanced upon infection with JEV, but suppressed in a dose-dependent manner by treatment with IFNα." (PMID 30261081, 2018). "Western blot demonstrated that MCL1 was upregulated after infection." (PMID 29072681, 2017). "SK3842 infection increased Mcl1 and reduced Bim and Puma in HT29." (PMID 28300841, 2017).
infection (continued). "This revealed that soon after infection, the virus could force the human cell to produce MCL-1, a protein that prevents cell death." (PMID 28425914, 2017). "We here tested whether Bcl-XL and Mcl-1 have different roles during the infection of mammalian cells with large DNA viruses." (PMID 27537523, 2016). "Infection with MVA deficient in F1L (MVAΔF1L) induced apoptosis in HeLa and MEFs 23 and was unable to protect Mcl-1-deficient MEFs against ABT-737." (PMID 27537523, 2016). "Infection of mature macrophages with MVA led to a loss of Mcl-1 but not Bcl-XL, similar to the events observed in the experiments in epithelial (HeLa) and MEF cells." (PMID 27537523, 2016). "Mcl-1 protein expression also increased following infection and the elevated levels were sustained." (PMID 27826299, 2016). "In particular, Mcl1 was very highly upregulated in guinea pig cells following Cm infection." (PMID 26779446, 2015). "The decline of pro-survival Mcl‐1 between 48 and 72 hours post infection is consistent with the in vivo lifespan of these cells and appears to constitute a potential molecular viability gate, which monocytes must negotiate in order to escape their intrinsic apoptotic fate." (PMID 24531335, 2014). "Described here and in a previous report sustained Mcl-1 expression and cytoprotection of macrophages by S. aureus following infection appears to be specific for this bacterium, since engulfment of Gram-negative bacteria or latex beads yielded negligible effects." (PMID 23431241, 2013). "A significantly more amount of the cleavage product was detected in IBV-infected, Mcl-1 knockdown H1299 (29%) and Huh7 (30%) cells at 20 hours post-infection, compared to the same infected cell lines treated with either siBak (0% in both cell lines) or siEGFP (23% in H1299 and 0% in Hun7)." (PMID 22253918, 2012). "In IBV-infected H1299 cells, significant induction of Mcl-1 (1.67–9.51 fold) was detected from 12–24 hours post-infection; however, relatively less efficient induction of Bak (1.09–2.83 fold) was observed as the basal level of Bak is much higher in this cell line." (PMID 22253918, 2012). "The involvement of MAP/ERK and PI3K kinase pathways in regulation of IBV-induced Mcl-1 was first studied by infection of Vero and H1299 cells with IBV at an M.O.I. of 2 in the presence or absence of either 20 mM of MAP/ERK kinase MEK-1 inhibitor U0126 or 40 mM of PI3K inhibitor LY294002." (PMID 22253918, 2012). "This is a specific effect, since infection with a control adenovirus encoding luciferase (adLuc) did not modify apoptosis and Mcl-1 silencing or overexpression did not modify expression of Bcl-XL or Bcl-2 (data not shown)." (PMID 21977009, 2011). "Interestingly, Mcl-1 and Bcl-2 levels remained constant in a time course infection experiment, indicating that regulation of these Bcl-2 family members does not account for the apoptosis resistance in Simkania infection." (PMID 21799887, 2011). "Following infection, immunoprecipitation indicated that Bik was bound to Mcl-1." (PMID 20152035, 2010). "C. trachomatis recruits BAD to its vacuole by unknown mechanism, which correlates with host-cell survival, and infection-induced upregulation of IAPs and Mcl-1 is required to keep the cells in an apoptosis resistant state." (PMID 20174550, 2010). "At this time the highest level of MCL1 expression was observed from the entire course of infection." (PMID 19381294, 2009). "Thus, Mcl-1 may be induced early in infection as part of the host’s effort to limit viral propagation through apoptosis or other antiviral mechanisms." (PMID 40951311, 2025). "In light of scientific research, Mcl-1 may determine the effectiveness of viral replication and dissemination, affect the host immune response, favor the persistence of infection, and influence the development of virus-driven diseases and pathological processes." (PMID 38256213, 2024). "Additionally, protein synthesis of MCL1 was significantly reduced by infection with JEV." (PMID 30261081, 2018).
infection (continued). "Although the molecular mechanisms of MCL1 protein expression in cells infected with Legionella remain unclear, the suppression of MCL1 through shut off of host translation might be part of the cellular innate response against infection with intracellular pathogens." (PMID 30261081, 2018). "Additionally, targeting Mcl-1 with the small molecule inhibitor A-121047725 in HeLa cells led to cell death, which could also be inhibited by preceding infection with MVA." (PMID 27537523, 2016). "We tested whether infection with these viruses also replaced Mcl-1 function." (PMID 27537523, 2016). "We showed for the first time that small inhibitory (si)RNA silencing of MCL1 in S. aureus-infected macrophages abrogates cytoprotection against staurosporine-induced apoptosis, confirming the role of Mcl-1 in sustaining the viability of macrophages during infection." (PMID 23431241, 2013). "The appearance of the PARP cleavage fragment in Bak-silenced Huh7 cells at 24 hours post-infection, albeit at lower levels as those in similarly infected Mcl-1 and EGFP knockdown Huh7 cells, could be attributed to a slight decrease in Mcl-1 expression in the Bak knockdown cells." (PMID 22253918, 2012). "In case these observations can be confirmed in future in vivo experiments, novel strategies to increase Mcl-1 or decrease Bim expression in pancreatic beta cells may turn to be interesting approaches to protect beta cells during infection by putative “diabetogenic” viruses." (PMID 21977009, 2011). "Thus activation of MAPK and upregulation of Mcl-1 may be a more general strategy in combating host cell apoptosis for successful infection." (PMID 18769617, 2008). "The initial phase of the infection cycle, characterized by full sensitivity of the host cell for apoptotic stimuli, is followed by a time window from about 16 to 24 hours post infection during which apoptosis resistance depends on the activation of host anti-apoptotic factors like IAPs and Mcl-1." (PMID 18769617, 2008). "Given that E. chaffeensis is known to increase the expression of anti-apoptotic B-cell lymphoma 2 (BCL-2) family members and myeloid cell leukemia 1 (MCL-1) is a transcriptional target of STAT3, we investigated MCL-1 expression during infection." (PMID 41115066, 2025). "Pharmacological inhibition of STAT3 significantly reduced MCL-1 expression and increased caspase cleavage, implicating STAT3 as a regulator of anti-apoptotic signaling during infection." (PMID 41115066, 2025). "STAT3 phosphorylation and nuclear translocation were detected beginning 48 h post-infection, coinciding with upregulation of STAT3 target genes, including the anti-apoptotic gene MCL-1." (PMID 41115066, 2025). "Consistent with the notion that NSs mediates MCL-1 down-regulation, MCL-1 abundance in RVFV△NSs-infected cells was comparable with the mock infected control cells, while infection with wild-type RVFV led to distinct MCL-1 down-regulation." (PMID 39213434, 2024). "Herein we show that either infection with MNV or expression of the NS3 protein alone, resulted in depletion of MCL-1 leading to apoptosis induction." (PMID 39226332, 2024). "Chlamydia trachomatis upregulates MCL-1 to inhibit Bax-induced apoptosis, and M. tuberculosis upregulates BCL-2 in macrophages during infection to prevent apoptosis." (PMID 37530530, 2023). "At 3h post-infection, we observed increased COX2 and MCL-1 protein levels in M. tb-infected compared to uninfected MDMs, and this increase was abrogated with CREB inhibition." (PMID 37000865, 2023). "In this study, we found MCL1 and PIP4K2B proteins upregulated after PAstV/SH/2022/CM1 infection, which were related to autophagy." (PMID 35891364, 2022). "Our findings that G-CSF treated neutrophils display increased expression of BCL-xL and MCL-1 is in agreement with these reports, and suggests that the upregulation of these anti-apoptotic genes may contribute to the increased viability of neutrophils during infection." (PMID 34322116, 2021).